APOE (apolipoprotein E)
Diseases named in the same sentence as APOE in open-access papers (continued):
Sharing a sentence is not in itself a finding about the gene and the disease.
type 1 diabetes (25 papers, 2011 to 2025). "In a streptozotocin injection-induced type 1 diabetes model, and in hyperlipidemic apolipoprotein E-knockout aging mice, HFD exacerbated hearing loss." (PMID 36810096, 2023). "Taken together, these data indicate that this model (STZ treated mice studied on an ApoE−/− background) is consistent with a type 1 diabetes phenotype and that LXA4 treatment had a minimum effect on the diabetic phenotype." (PMID 39563316, 2024). "In support of a defect in the clearance capacity of chylomicron remnants, apoE levels where lower in patients with type 1 diabetes." (PMID 24959195, 2014). "High apoB-48, low apoE, and a decrease in PON-1 activity (anti-oxidative capacity of HDL) together with impaired AIx response suggest that patients with type 1 diabetes are likely at higher risk of vascular dysfunction and cardiovascular disease." (PMID 24959195, 2014). "Previous studies in hyperlipidemic rats with non-insulin-dependent diabetes or hypercholesterolemic uremic atherosclerotic ApoE KO mice reported a decreased renal klotho gene expression." (PMID 24386260, 2013). "Increased right ventricular weight compared to the left ventricle plus the septum weight has been described in streptozotocin-induced type 1 diabetes and in insulin resistant ApoE knockout mice." (PMID 21513515, 2011). "(2013) reported that S100A8/S100A9 acted through the receptor for advanced glycation end-products (RAGE) on CMPs to promotegranulocyte–macrophage colony-stimulating factor (GM-CSF) production that in turn stimulated GMP proliferation and myelopoiesis in type 1 diabetic mice and apoE−/− mice." (PMID 36866528, 2023). "Indeed, mice lacking Apo-E (apoE−/−) with induced type 1 diabetes had at least a 3-fold increase in atherosclerotic lesions." (PMID 41516038, 2025).
colorectal cancer (24 papers, 2009 to 2026). A primary or metastatic malignant neoplasm that affects the colon or rectum. "For instance, in colorectal cancer, APOE enhances tumor cell migration and invasion through the Jun-APOE-LRP1 signaling axis." (PMID 40745073, 2026). "In colorectal cancer, patients with the APOE ε2/ε3 genotype are more likely to progress to advanced stages once diagnosed." (PMID 39763652, 2024). "A statistically significant association has been reported between APOE ε4 and elevated levels of VLDL-C and TG in colorectal cancer patients." (PMID 36057714, 2022). "There are several studies which have identified single gene like PDL-1, Layilin and Apolipoprotein E with prognostic significance in colorectal cancer." (PMID 31387239, 2019). "In the cohort of the liver metastasis, the ApoE expression was increasing in normal mucosa tissue, primary colorectal cancer (PC), and colorectal liver metastases (CLM) in order." (PMID 30631342, 2018). "Furthermore, APOE has been shown to enhance the migration and invasion capabilities of colorectal cancer cells by interacting with low‐density lipoprotein receptor‐associated protein 1 (LRP1)." (PMID 40437660, 2025). "For instance, APOE ε2 reduces the risk of developing colorectal cancer, while the APOE ε4 allele does not significantly impact colorectal cancer risk, In contrast, the APOE ε3 allele is linked to a higher risk of laryngeal squamous cell carcinoma (LSCC)." (PMID 39763652, 2024). "Whereas, ApoE-/- specifically activated 5 pathways (integrin, interferon, crosstalk between DC and NK cells, colorectal cancer metastasis, ephrin receptor) and suppressed 5 pathways (phenylalanine degradation IV, PCP, BAG2 and complement system) only in Ly6Clow MC." (PMID 34987524, 2021). "Several DEPs, such as APOE, APOA1, and APOL1, are known as representative HDL-associated molecules; however, they were excluded as biomarker candidates due to high fold changes observed in pancreatic or colorectal cancers." (PMID 33808296, 2021). "However, the impact of apoE on colorectal cancer (CRC) metastasis remains largely unexplored." (PMID 37310025, 2023). "In our investigation, RT-q PCR was utilized to ascertain the expression levels of C5AR1, APOE, CYP1B1, and SPP1 in a standard colon cell line and three colorectal cancer cell lines." (PMID 39494300, 2024). "There is a favourable correlation between the proportion of APOE+CTSZ+CD14+ cells and regulatory T cells in colorectal cancer samples." (PMID 39187937, 2024). "In colorectal cancer patients, white blood cell count, platelet, ApoA, FFA, IL-6 and TNF-α increase significantly, while albumin, prealbumin and ApoE decreased significantly." (PMID 31788012, 2019). "Furthermore, a significant abundance of APOE+CTSZ+CD14+ cells, which exhibit immunosuppressive properties by increasing the expression of anti‐inflammatory genes, has been detected in a substantial number of tumour specimens, specifically in cases of colorectal cancer." (PMID 39187937, 2024).
sleep disorder (24 papers, 2015 to 2025). A change from the patient's baseline sleeping pattern, in the hours slept and/or an alteration/dysfunction in the stages of sleep. "A systematic review has investigated the association between sleep disorders and APOE ε4 status in individuals with MCI and AD." (PMID 38223295, 2024). "A number of studies presented contradictory results on the relation between APOE and its variants and sleep disorders." (PMID 32630105, 2020). "Another fascinating set of data proposed that there is a significant association between sleep disorders and APOE genotype, as well as among APOE, sleep-wake cycle, and deposition of β-amyloid." (PMID 30677746, 2019). "It was discussed that APOE ε4 allele could be associated with sleep disorders, tau phosphorylation, and Aβ deposition." (PMID 30719245, 2018). "On the other hand, the association of APOE with sleep disorders is also proven." (PMID 30719245, 2018). "This study focused on whether ApoE deficiency leads to CRDs, by what mechanisms the CRDs occur, and by what means the CRDs can be rescued, aiming to identify novel curative strategies to treat the sleep disorders and CRDs in AD patients." (PMID 27824104, 2016). "Multiple investigations have demonstrated that APOE ε4 significantly increases vulnerability to sleep disorders, including compromised sleep quality, altered sleep duration, and difficulties with sleep initiation or maintenance in cognitively normal adults." (PMID 41040811, 2025). "The study included 1,000 CN participants, including 134 individuals with sleep disturbances and 306 APOE ε4 carriers (APOE ε4+)." (PMID 41040811, 2025). "The University of Toronto (37 publications) and McGill University (33 publications) in Canada investigate the interaction between the APOE ε4 gene and sleep disorders through extensive inter-institutional collaboration (49/50 links)." (PMID 40264463, 2025). "BPSD in the patients’ group were evaluated with NPI, PHQ-9 and the sleeping disorders questionnaire; then, they were analyzed for associations with the genetic variants of PER2, PER3, OX2R and APOE." (PMID 36901420, 2023). "Additionally, we found that APOE ε4 carriers with sleep disorder had the highest plasma NfL and GFAP compared to the other groups." (PMID 38421124, 2024). "Although we adjusted for numerous confounding factors in our analyses, unmeasured covariates might still lead to confounding bias, including sleep disorders and APOE status." (PMID 36289469, 2022). "Only one clinical study showed elevated GFAP levels as an indicator of disrupted sleep and sleep‐related disorders in individuals at risk for AD—in particular, for APOE ε4 carriers with sleep disorder who had the highest plasma GFAP compared to non-carriers with or without sleep disorder." (PMID 40690136, 2025). "Fourth, despite our adjustment for a broader range of confounders, unmeasured covariates, such as apolipoprotein E status, sleep disorders, naps, and medication use affecting sleep (e.g., hypnotics, opioids, and psychotropic medications) might have introduced bias." (PMID 39692596, 2025). "Furthermore, the relationship among sleep disturbances, APOE status, and astrocytic activation might offer novel avenues for therapeutic interventions targeting both sleep disorders and neurodegenerative conditions." (PMID 38421124, 2024). "Unfortunately, ApoE type, sleeping disorder, and physical activities were not evaluated." (PMID 36034127, 2022).
arteriosclerosis (23 papers, 2009 to 2024). A vascular disorder characterized by thickening and hardening of the walls of the arteries. "AR-C17 can protect against arteriosclerosis in endothelial cells and apolipoprotein E-deficient mice by modulating Sirt3 signaling." (PMID 38613012, 2024). "ApoE-deficient mice are also considered one of the models of human arteriosclerosis because the onset site and progression of the lesion are similar to those of humans." (PMID 37396111, 2023). "Meanwhile, RSV decreased TMAO levels by inhibiting commensal microbial trimethylamine (TMA) production via gut microbiota remodeling in ApoE−/− mice, thus reducing arteriosclerosis risk." (PMID 34946029, 2021). "RAS signaling was found to accelerate arterial senescence and arteriosclerosis in human VSMCs and an atherosclerotic apolipoprotein E-deficient (ApoE KO) mouse model." (PMID 34869701, 2021). "CHOP deficiency also decreases the expression of inflammatory cytokines in arteries and suppresses arteriosclerosis in apoE-deficient mice." (PMID 24204574, 2013). "In apoE-deficient mice, a well-characterized model for arteriosclerosis, inhibition of IL-17A signalling reduced atherosclerotic lesion formation, prevented plaque rupture, and diminished levels of circulating proinflammatory cytokines." (PMID 23468966, 2013). "The expression of Sirt6 in macrophage foam cells was examined in atherosclerotic plaques from ApoE−/− mice fed a western diet for 16 weeks to determine if macrophagic Sirt6 involved in the progression of arteriosclerosis." (PMID 37736721, 2023). "The oil red O staining results also showed that DXXK treatment inhibited lipid accumulation in the liver tissue and diminished arteriosclerosis plaque formation in ApoE–/– mice." (PMID 30443213, 2018). "Arteriosclerotic plaques that develop in the ApoE-/- arteriosclerosis mouse model can not only be localised in the aortic valves but also quantified by volume measurements." (PMID 28178293, 2017). "A human driver-1-related, ApoE −/− mouse model, is that which best fits the study of arteriosclerosis and diabetes-accelerated arteriosclerosis." (PMID 27378910, 2016). "Both APOE and periodontal disease are known etiologies or complicating factors for arteriosclerosis and its manifestations." (PMID 19208189, 2009). "Similarly, Hsp90 inhibition suppresses lipopolysaccharide-induced endothelial inflammation and arteriosclerosis inflammation in ApoE mice." (PMID 35193709, 2022). "However, this study was conducted in animals by using ApoE knockout animals as a model for arteriosclerosis." (PMID 32967121, 2020). "In addition, we demonstrate that by PTA staining of hearts from an ApoE-/- arteriosclerosis mouse model, arteriosclerotic plaques in the aortic valve region can not only be precisely localized in 3D but their volumes can also be quantified." (PMID 28178293, 2017). "In order to proof the applicability of the μCT-based histological approach in combination with PTA staining to assess aortic plaque formation, we analysed hearts of 12 weeks old female mice fed for 70 day with a high fat diet from the well described ApoE-/- arteriosclerosis mouse model." (PMID 28178293, 2017). "Furthermore, administration of adiponectin with adenovirus vector suppressed the progression of arteriosclerosis in apolipoprotein E-knockout mouse, which is the animal model for arteriosclerosis." (PMID 25592402, 2015). "In this study, the effects of miR-185-5p on attenuating arteriosclerosis and lipid accumulation were explored using HFD-fed apoE-/- mice and ox-LDL-stimulated macrophages." (PMID 35172278, 2022). "ApoE also affects the immune response, and in mice, ApoE KO increased the expression of Toll-like receptor 4 (TLR4) and LOX-1, suggesting the formation of foam cells and promoting the onset of arteriosclerosis." (PMID 35955522, 2022).
intracerebral hemorrhage (22 papers, 2012 to 2025). A cerebrovascular disorder characterized by bleeding into one or both cerebral hemispheres including the basal ganglia and the cerebral cortex. "In a cross-sectional study of 2 different cohorts for a total of 412 patients with known brain arteriovenous malformation, carriers of APOE ε4 variants had a 4-fold increase in the risk of sustaining an intracerebral hemorrhage." (PMID 38363572, 2024). "Are apolipoprotein (APOE) ε4 variants associated with the occurrence of intracerebral hemorrhage in patients with brain arteriovenous malformation?" (PMID 38363572, 2024). "An independent study discovered that the APOE ε4 allele is an independent risk factor for recurrent intracerebral hemorrhage in hypertensive individuals of Indian descent." (PMID 38540308, 2024). "The CT and APOE genotype prediction model for CAA-associated lobar intracerebral haemorrhage shows excellent discrimination in this cohort, but requires external validation." (PMID 29331631, 2018). "Recent studies have also found similarities between intracerebral hemorrhage and microbleeds with regard to shared risk factors, i.e. APOE, hypertension, and lipid profile [25•, 44]." (PMID 22538431, 2012). "So far, only the APOE gene has been identified as a robust genetic risk factor for intracerebral hemorrhage." (PMID 22538431, 2012). "This cross-sectional study uses UK Biobank and All of Us Research Program data to assess whether APOE ε4 is associated with higher risk of intracerebral hemorrhage among patients with known brain arteriovenous malformation." (PMID 38363572, 2024). "This case-control study examines whether the risk for intracerebral hemorrhage presented by apolipoprotein E ε4 and ε2 alleles varies by race/ethnicity." (PMID 30726504, 2019). "Although three out of four patients from our centre were heterozygous for either ε2 or ε4 alleles of APOE—known CAA susceptibility alleles, widespread CAA and presentation with intracerebral haemorrhages at such a young age would still be highly unusual even for carriers of APOE risk alleles." (PMID 29450646, 2018). "Specifically, recent study has demonstrated that the COG1410, an APOE-mimic peptide, strongly alleviates the neuroinflammation and neuronal apoptosis in mice with intracerebral hemorrhage, and TREM2/PI3K/Akt signal pathway involved in the cellular events." (PMID 37658943, 2023). "We were able to develop a highly discriminatory and well calibrated prediction model using subarachnoid haemorrhage and finger-like projections from intracerebral haemorrhage on CT, and APOE ɛ4 possession, which was internally validated." (PMID 29331631, 2018). "Other tests that can diagnose CAA include CT, which is usually the first test to diagnose intracerebral haemorrhage, and APOE genotype." (PMID 29331631, 2018). "Intracerebral hemorrhage has been associated with APOE ε4, however, no such relationship was seen in our cohort." (PMID 35912087, 2022). "Subarachnoid haemorrhage and APOE ɛ4 possession or finger-like projections, separated high from low or medium probability groups, and had a specificity of 96% (95% CI 78–100) meaning that the presence of these predictors with lobar intracerebral haemorrhage ruled in moderate or severe CAA." (PMID 29331631, 2018).
asthma (21 papers, 2009 to 2025). "In all three APOE groups, the attention domain was enriched for genes associated with inflammatory and autoimmune-related diseases such as asthma, celiac disease, and lupus." (PMID 40725187, 2025). "In addition, galiellalactone ameliorated inflammation and thrombosis in a model of Apolipoprotein E (ApoE)—deficient mice and reduced experimental asthma." (PMID 28824460, 2017). "For example, APOE ε4 cannot be intervened as a genetic marker, while the inflammatory pathways of asthma (such as IL‐7R signaling) can be targeted through drugs (such as anti‐IL‐7R antibodies) or lifestyle adjustments." (PMID 40951943, 2025). "OVA-treatment significantly increased the number of eosinophils in BLAF, the formation of collagen fibers, and the infiltration of inflammatory cells in pleural cavity in ApoE-/-, suggesting asthma was successfully induced with OVA." (PMID 31440377, 2019). "APOE also has been shown to have protective roles in murine models of asthma, acute lung injury (ALI), emphysema, and pulmonary hypertension." (PMID 30412599, 2018). "Recently, Levine and co-workers showed that asthma-like traits are enhanced in ApoE−/− mice when exposed to house dust mite extracts in the form of an allergen." (PMID 27538678, 2016). "Yao’s experiment discovered that apolipoprotein E or apolipoprotein A-I mimetic peptides could attenuate experimental asthma in the murine model, possibly by reducing pulmonary eosinophil infiltration." (PMID 37168867, 2023). "However, a number of laboratories reported the failure of scrambled form of 4F to inhibit effects of LPS in in vivo experiment as well as to reproduce anti-inflammatory and anti-oxidant effects of 4F in apoE null mice and in murine model of asthma." (PMID 23691230, 2013). "Furthermore, it was well documented that ApoE mimetic peptides were novel treatment approaches for asthma." (PMID 24324506, 2013). "On the other hand, apoE may lead to pro-inflammatory events in the lung and can function as a concentration-dependent pulmonary danger signal that augments pulmonary inflammatory responses in asthma-related airway conditions." (PMID 35359998, 2022). "This hypothesis is further complemented by the M2 polarization profile (APOE, TXN, TGM2, STING1, NAMPT) enriched in this group, a dominant macrophage profile in high Th2-type asthma in humans and one known to activate the Th2 response with downstream eosinophilic infiltration and airway remodeling." (PMID 39594673, 2024). "Among the top genes are ones that have been previously related to asthma (e.g., APOE, CHI3L1, EGR1, MYH11, OXTR, SERPINB2, SOCS3) and corticosteroid-resistant asthma (e.g., FOS) though not necessarily in humans or via changes of the ASM." (PMID 26207385, 2015).